TNF (tumor necrosis factor)
Diseases named in the same sentence as TNF in open-access papers (continued):
Sharing a sentence is not in itself a finding about the gene and the disease.
renal fibrosis (continued). "Furthermore, miR-455-3p also inhibits renal fibrosis by targeting ROCK2, together with the reduction of anti-inflammatory cytokines such as tumor necrosis factor-α (TNF-α) and monocyte chemotactic protein 1 (MCP-1)." (PMID 33574750, 2020). "To investigate the potential mechanism for the downregulation of JLP during UUO induced renal fibrosis, we treated cultured HK-2 cells, in which JLP was abundantly expressed, with TNF-α, TGF-β1, and FGF-2, which are the key initiators of inflammatory and fibrotic lesions." (PMID 32504044, 2020). "Real‐time PCR analysis found elevated levels of mRNA for markers of renal inflammation (CD68, TNF‐α, CCL2) and renal fibrosis (TGF‐β1, fibronectin, collagens I and IV) in diabetic compared to nondiabetic kidneys, which were not different in male and female mice." (PMID 31535473, 2019). "Anti-TNF-α biologics such as infliximab, adalimumab or etanercept have not been shown to be successful in the treatment of renal fibrosis." (PMID 28507324, 2017). "Fibrosis reduction: MSCs decrease the levels of profibrotic factors such as IL-6, IL-1β, TNF-α, TGF-β, α-SMA, collagen I, and collagen IV while increasing the levels of antifibrotic factors such as FGFs, HGF, and VEGF, all of which inhibits EMT and reduces renal fibrosis." (PMID 40093796, 2025). "However, today there are no data showing the combined effect of TMAO and TNF-α on renal fibrosis-and inflammation." (PMID 38643262, 2024). "Similar to the findings in renal fibrosis, the 8-week-treatment with SIS3 in established db/db mice from 8 to 16 weeks significantly inhibited renal inflammation by suppressing F4/80+ macrophage infiltration and a marked upregulation of MCP-1, IL-1β, and TNF-α both locally and systematically." (PMID 38164169, 2024). "Tubular cells, when damaged during renal fibrosis, transition to a secretory phenotype and generate fibrogenic agents such as sonic hedgehog (Shh), Wnt ligands, and TGF-β, as well as IL-6, monocyte chemotactic protein-1, TNF-α, and other inflammatory cytokines." (PMID 38808357, 2024). "Thus, Siglec-F+ neutrophils may contribute to renal fibrosis by 2 mechanisms, namely, by activating fibroblasts via their profibrotic cytokines (TGF-β1, TNF-α, and IL-1β) and by directly secreting COL1A1." (PMID 35482420, 2022). "In addition, molecular detection showed that MSCs might reduce the expression of renal fibrosis-related indicators, such as TGF-β, Col-I, FN, α-SMA, and E-cadherin, and the expression of inflammatory mediators such as MCP-1 and TNF-α." (PMID 33413678, 2021). "Our results indicated that the administration of MA inhibits the expression of pro-inflammatory cytokines and cell adhesion molecules such as IL-1β, TNF-α, MCP-1, and ICAM-1, suggesting that MA may ameliorate renal fibrosis by the inhibition of inflammatory response." (PMID 34588982, 2021). "It was preliminarily confirmed that PS could inhibit the release and expression of inflammatory factors such as TGF-β1, TNF-α, and IL-1β by regulating the TGF-β1/p38MAPK/NF-κB signaling pathway, to improve renal tissue injury, inflammatory factor infiltration, and renal fibrosis in GN rats." (PMID 33312224, 2020). "In wild type mice, ADR injection induced proteinuria, renal fibrosis, and increased macrophage infiltration into glomeruli (q-PCR and immnohistochemical staining of F4/80 in kidney sections) and increased production of pro-inflammatory cytokines (q-PCR for MCP-1, CD11c, TNF-α, and IL-1β)." (PMID 27196103, 2016).
renal fibrosis (continued). "Immunohistochemistry, western blot, and real-time PCR also showed that restored renal Smad7 blocked AA-induced severe renal fibrosis such as upregulation of collagen I and α-SMA and inhibited renal inflammation including F4/80+ macrophages and CD3+ T cells and upregulation of MCP-1 and TNFα." (PMID 25883225, 2015). "In addition, SMAD2 and SMAD3 knockout augmented the production of inflammatory factor (TNFα and IL-6), while SIRT2-mediated NLRP3 deacetylation protects against inflammation, indicating SIRT2 may be a more attractive target to improving renal fibrosis." (PMID 37777567, 2023). "Indeed, the renal fibrosis indicators (i.e., FN, COL-IV, COL-1); the tubular damage indicator (i.e., KIM-1); the inflammatory indicators (i.e., TNF-α, MCP-1 and IL-1β); the oxidative stress indicators (i.e., 8-OHdG and 4-HNE) were all increased when albuminuria developed." (PMID 33811534, 2021). "Although the direct causal relation between FGF2 and renal fibrosis has not been demonstrated yet, FGF2 is associated with TGFβ-induced proliferation of renal fibroblast, together with the induction of other profibrotic signaling molecules including Wnt4 and TNF-α." (PMID 32410988, 2020). "As in the case of such anti-TNF-α therapy, anti-TGF-β1 agents such as pirfenidone have not been shown to be successful in the treatment of renal fibrosis." (PMID 28507324, 2017). "Additionally, they reported increased expression of TNF-α in macrophages, but not in renal parenchymal cell lines, in culture after 12 h incubation with rMBL and suggest that MBL promotes renal fibrosis via crosstalk with mesangial and tubular epithelial cells." (PMID 39000309, 2024).
spondyloarthritis (167 papers, 2006 to 2025). "Cytokine-mediated inflammation involving IL-1/NLRP3, TNF-α, IL-6, and IL-17 pathways has been implicated in both spondyloarthritis and pericardial disease." (PMID 41357030, 2025). "Co-existence with spondyloarthritis (SA) has been more described as an adverse effect of anti-TNF α therapy than an association." (PMID 29387328, 2018). "In addition to DKK1, the dual blockade of TNF and IL-17A was reported to ameliorate inflammation and structural damage in a rat model of spondyloarthritis, suggesting that TNF and IL-17A have pathogenic effects on bone metabolism." (PMID 37798786, 2023). "Therefore, the TgA86 mouse represents a valuable model for deciphering the role of transmembrane TNF in the pathogenic mechanisms of spondyloarthritis and for assessing the efficacy of human therapeutics targeting different phases of the disease." (PMID 33023659, 2020). "Furthermore, the secretion of IL-17A and TNF-α contributes to the bone loss observed in spondyloarthropathies." (PMID 32707785, 2020). "We investigated whether polymorphisms (SNPs) in the promoter region of TNFA, or in the autoinflammatory TNFRSF1A and MEFV genes, concur with HLA-B27 in enhancing the risk of Spondyloarthritis (SpA) and/or in predicting the response to anti-TNFα treatment." (PMID 29579081, 2018). "An Israeli study reported a decreased frequency of the number of all-cause hospitalizations during anti-TNF treatment compared to the period before treatment among patients with RA and spondyloarthropathies (44.2 versus 74.2 hospitalizations/100 py, p-value < 0.0001)." (PMID 27431503, 2016). "For example, the pathogenesis of spondyloarthritis (SpA) is particularly driven by the HLA-B27 antigen, activating T cells and producing pro-inflammatory cytokines such as tumor necrosis factor (TNF) and interleukin-17 (IL-17)." (PMID 40647710, 2025). "In contrast to other spondyloarthropathies, IBD is primarily associated with genetic variations in the promoter region of the tumor necrosis factor (TNF) gene." (PMID 40095525, 2025). "In cases of concomitant spondyloarthropathies, therapies including anti-TNF agents or upadacitinib are recommended." (PMID 39860594, 2025). "Consistent with our imputed findings, IL-27 treatment prior to disease onset in the HLA-B27-transgenic rat spondyloarthritis model inhibited spondyloarthritis development through suppression of IL-17/TNF production by CD4 + T-cells." (PMID 40709250, 2025). "A study involving a cohort of over 42 spondyloarthritis (SpA) patients found that anti-TNF therapy demonstrated acceptable safety and a positive response rate in SpA patients." (PMID 40469293, 2025). "The timely initiation of tumor necrosis factor (TNF) blocking agents plays a critical role in the successful management of spondyloarthropathies by substantially reducing disease activity, leading to improved symptoms and radiographic sacroiliitis outcomes." (PMID 38415452, 2024). "in their study among 15 spondyloarthritis reported an increase in SARS-CoV-2 specific antibody titers after the 3rd dose in both TNF-a and/or IL-17 recipients." (PMID 38979481, 2024). "Spondyloarthritis pathogenesis is related to the hyperproduction of proinflammatory cytokines (TNFα, IL-17A, IL-23, etc.)." (PMID 37238999, 2023). "The effectiveness of biologic therapies, primarily tumor necrosis factor inhibitors (TNFi), for children with spondyloarthritis (SpA) has made inactive disease a realistic patient outcome." (PMID 36755328, 2023). "It was shown that IL-17A inhibition is more effective as compared to TNFα inhibition in terms of the radiological progression of spondyloarthritis." (PMID 37238999, 2023). "Biologics such as tumor necrosis factor-α have shown good anti-inflammatory effects in the treatment of spondyloarthritis." (PMID 37920462, 2023).
spondyloarthritis (continued). "Another study compared 296 patients with spondyloarthropathy (of which 198 had AS) receiving anti-TNF-α agents (IFX/ADA/ETN) with 112 patients taking disease modifying antirheumatic drugs (DMARDs), to evaluate the paradoxical IBD development." (PMID 37629636, 2023). "Agents targeting TNF are widely used in the treatment of PsA, PsO, RA, spondyloarthropathies, and IBD and include infliximab, etanercept, adalimumab, golimumab, and certolizumab pegol." (PMID 35214755, 2022). "The tumor necrosis factor (TNF) and IL-23/IL-17 axes are the main therapeutic targets in spondyloarthritis." (PMID 35055042, 2022). "Other new biologic response modifiers that target IL-23 or IL-17, especially IL-17, are being considered as an alternative to anti-TNF-α antagonists in treatment of seronegative spondyloarthropathies." (PMID 34394873, 2021). "Important activators of TAK1-dependent receptor-mediated signaling in inflammatory settings—such as spondyloarthropathies—include IL-1, IL-17, TNF-alpha as well as other cytokines." (PMID 32707785, 2020). "Exposure of the immune system to microorganisms is important for spondyloarthropathy pathogenesis, and several cytokines play a key role in the inflammatory process, including tumor necrosis factor (TNF)." (PMID 32938495, 2020). "In this study, 89% of patients with RA had already received at least one bDMARD and 87.8% of those with spondyloarthritis had already received anti-tumor necrosis factor α." (PMID 31877764, 2019). "At present, there are five TNF-inhibitors approved for the treatment of spondyloarthritis in the UE, the USA and many other countries." (PMID 30941119, 2019). "We performed 16S rDNA sequencing of 38 stool samples from 19 spondyloarthritis patients before and three months after anti-TNF-α treatment onset." (PMID 29615661, 2018). "This is supported by the finding reported in patients with spondyloarthritis (SpA) treated with TNF-α antagonist: serum YKL-40 concentrations decreased during successful anti-TNF-α treatment whereas YKL-40 levels remained high in non-responding patients." (PMID 28841649, 2017). "Spondyloarthritis subject macrophages correspondingly produced more TNF-α in response to lipopolysaccharide (LPS, p = 0.015)." (PMID 28791018, 2017). "Anti-tumor necrosis factor (anti-TNF) agents are an effective, but costly, treatment for spondyloarthritis (SpA)." (PMID 28904528, 2017). "The introduction of tumor necrosis factor (TNF) inhibitors has improved the management of spondyloarthritis (SpA) tremendously." (PMID 27784336, 2016). "While previous studies have researched in association analyses between TNFα promoter polymorphisms and responses to TNF blockers in spondyloarthritis patients, their results were conflicting." (PMID 27578555, 2016). "Given that γδT cells can produce the pro-inflammatory cytokines TNFα and IFNγ, which are involved in the pathogenesis of RA and spondyloarthritis, it is possible that pregnancy induces some dampening of the TNFα- or IFNγ-producing Vδ1 and Vδ2 cells." (PMID 26795030, 2016). "Dose reduction schedules of tumor necrosis factor antagonists (anti-TNF) as maintenance therapy in patients with spondyloarthritis are used empirically in clinical practice, despite the lack of clinical trials providing evidence for this practice." (PMID 26289076, 2015). "Anti-TNF agents, for example, provide great benefit to patients with RA, spondyloarthritis, Ps, and intestinal inflammatory diseases." (PMID 24980068, 2015). "Early diagnosis makes biological (tumor necrosis factor alpha blockade) treatment possible which is effective in early phase of spondyloarthropathies." (PMID 25800592, 2015). "Anti-TNF-α agents also improve endothelium-dependent vasodilation in patients with spondyloarthritis, cutaneous psoriasis and IBD, although studies are small and few." (PMID 24968272, 2014).
spondyloarthritis (continued). "Anti-TNF drugs have proven to be effective against spondyloarthritis (SpA), although 30% of patients fail to respond or experience adverse events leading to treatment discontinuation." (PMID 23890223, 2013). "The blockade of TNF-α-mediated events has been found to have significant therapeutic effects on active RA and seronegative spondyloarthropathies." (PMID 24256769, 2013). "The introduction of TNFα antagonists (anti-TNFα) has revolutionised the management of patients with spondyloarthritis (SpA)." (PMID 22404969, 2012). "The treatment is based almost entirely on extrapolation from treatment of other forms of spondyloarthropathies since they shared the same pathogenesis, which involves significant expression of TNF-α in the joint spaces as the major inflammatory mediators." (PMID 22236863, 2012). "The anti-TNF monoclonal antibodies that act by neutralizing TNF have proved highly effective in AS therapy, but also in the treatment of other spondyloarthropathies." (PMID 22721554, 2012). "There is now accumulating evidence that targeted anti-TNF-α therapy is highly effective in spondyloarthritis." (PMID 22229035, 2012). "The aim of this study was to evaluate, under real-life conditions, the safety and efficacy of tocilizumab in patients having failed anti-TNFα therapy for spondyloarthritis." (PMID 22404969, 2012). "Several studies have shown that TNF blockade improves clinical, biochemical, immunological, and MRI markers of inflammation in adults with undifferentiated spondyloarthritis." (PMID 21722401, 2011). "This study represents the first evaluation of the effectiveness of adalimumab in patients with spondyloarthritis (AS and PsA) who had previously been treated with one or two other TNF antagonists." (PMID 20553600, 2010). "The rapid decrease ofserum MMP-3 level after TNF blocking therapy is in line with earlier observations inpatients with spondyloarthritis (SpA)." (PMID 20844595, 2010). "A Swedish study of anti-TNF use in RA, PsA, and other spondylarthropathies has suggested that utility improvements occur rapidly (within 2 weeks) and were maintained thereafter." (PMID 20391480, 2010). "This suggestion is strengthened by the fact that anti-TNF treatment during 2 years in patients with spondyloarthropathy resulted in significant increase in body weight mainly due to gain in fat mass." (PMID 20964833, 2010). "Patients with spondyloarthritis have abnormal immune cells and immune molecules in their peripheral blood, such as T lymphocytes, B lymphocytes, macrophages, and changes in cytokines like interleukin-1, interleukin-6, and tumor necrosis factor (TNF)-α." (PMID 39877611, 2025). "Baseline BMD, anti-TNFα treatment, and disease activity markers were predictive of BMD loss and subsequent osteoporotic fractures in patients with spondyloarthropathies, highlighting the need for regular follow-up to monitor these parameters and adjust treatment accordingly." (PMID 39518518, 2024). "Moreover, patients under treatment with TNFα inhibitor antibodies have predominantly mild flares, and its efficacy in preventing relapses of rheumatological manifestations of spondyloarthropathies is strongly evidenced." (PMID 37646883, 2023). "Spondyloarthritis and HS share key inflammatory mediators including TNF, IL-1, and IL-17, which may suggest a biological link between these conditions." (PMID 33493574, 2022). "In this study, we hypothesized that the dual blockade of TNF and IL-17A would effectively reduce both inflammation and structural damage in the context of spondyloarthritis." (PMID 35055042, 2022). "We assessed the effects of 5 weeks of dual blockade of TNF and IL-17A, TNF inhibitor monotherapy, and IL-17A inhibitor monotherapy, compared to vehicle control, on the severity and the extent of spondyloarthritis manifestations in the M. tub.-induced HLA-B27/huB2m tg rats." (PMID 35055042, 2022).